CA9 (carbonic anhydrase 9)
Diseases named in the same sentence as CA9 in open-access papers (continued):
Sharing a sentence is not in itself a finding about the gene and the disease.
tumor (continued). "Results showed that the average of tumor growth rate of untreated mice strongly correlates to the expression level of both MCM2 and Ca9 genes (Pearson’s correlation values 0.8397 (t test 0.0002) and 0.8841 (t test 0.0001), respectively)." (PMID 33153038, 2020). "Of note, expression of carbonic anhydrase 9, a typical marker of hypoxia, was also reduced in HIF-1α-KD tumor cells." (PMID 33142239, 2020). "Both ISH and RNA-Seq data demonstrated that diverse regions of the tumor can be delineated based on CD44 and CA9 expression whose pattern was correlated." (PMID 32823815, 2020). "Using the previous approach, we found a significant increase in CA9 and LOX expression in tumor tissue, which was significantly more pronounced in CD68High patients." (PMID 32231135, 2020). "Another study in 2019 suggested the co-localization of CA9 with phosphorylated ezrin (EZR), activated the hypoxia–autophagy–EZR pathway in tumor-initiating human cells and primary CRC tissues, proving its clinical relevance." (PMID 32630086, 2020). "To overcome these limitations of EpCAM, we decided to test CD147, CA9, and CD70 as potential tumor markers for ccRCC." (PMID 33276608, 2020). "In contrast to EpCAM, CA9, CD70, and CD147 represent promising tumor-specific biomarkers for EVs in ccRCC." (PMID 33276608, 2020). "Primarily due to the unique position of HRE within the CA9 promoter, CA IX is considered as one of the best endogenous sensors of HIF-1 activity and thus serves as a reliable marker of tumor hypoxia." (PMID 31905844, 2019). "Tumor samples from 72 OSCC patients and 24 samples of normal tissue were analyzed for CA9 mRNA levels." (PMID 30654595, 2019). "We then stained the tumor sections taken from these mice with CA9 (a hypoxia marker) and FABP4; we observed co-localization of FABP4 with CA9." (PMID 30050129, 2018). "In our study 44% of the measured CA9 tumour pHe values were below 6.7, whereas the EV tumours had only 15%, showing that CA9 tumours produced sufficient CAIX-related acidification in vivo to favour invasion and/or metastatic cell escape." (PMID 30206370, 2018). "We measured ascorbate, HIF-1α, and HIF-2α protein and HIF downstream targets BNIP3, CA9, cyclin D1, GLUT1, and VEGF (combined to generate the HIF pathway score) in VHL-defective ccRCC (n = 73) and VHL-proficient pRCC human tumor tissue (n = 41)." (PMID 30555801, 2018). "In the primary tumor of Cases 1, 4 and 7, the expression patterns of GGT1 and CA9 were similar, while the expression patterns of GGT1 and CA9 were different in Cases 2, 3, 5, 6, and 8–12." (PMID 30542087, 2018). "We expand those studies, comparing drug responses using patient-derived PDAC cells displaying differential hypoxic responses in 3D spheroid tumor-stroma models to characterize second generation APE1/Ref-1 redox signaling and CA9 inhibitors." (PMID 30214007, 2018). "The inside of mLN exhibited central necrosis, and expression of CA9 and GGT1 was higher than that in the primary tumor, despite the small size of the mLNs, suggesting that blood supply did not depend on size." (PMID 30542087, 2018). "48.5% of all patients showed mainly membranous CA9 expression correlating with younger age, female sex, higher AFP levels, tumor size grading and even survival." (PMID 30011326, 2018). "Immunohistochemically, the tumor cells were strongly positive for CK7, EMA, vimentin, SOX10, S-100, and focally positive for CA9." (PMID 29041930, 2017). "Tumor xenograft initiation was reduced by 40% in CA9-ko and NHE1/CA9-dko groups while 100% initiation occurred in WT and NHE1-ko tumors." (PMID 28055960, 2017). "Protein extracts from tumor xenografts confirmed that the NHE1 and CA9 knockout phenotype induced by ZFN and CRISPR-cas9 was maintained." (PMID 28055960, 2017). "Our use of the aggressively growing LS174 tumor cell xenograft model revealed striking tumor growth reductions in both NHE1-ko and CA9-ko conditions." (PMID 28055960, 2017).
tumor (continued). "Phosphorylation of CA9 modulates its activity, implicating PKA in tumor invasion in part by regulation of carbonic anhydrases and extracellular pH." (PMID 28304380, 2017). "Indirect methods consist essentially of immunohistochemical measurement in tumor biopsies of the expression of HIF-1 alpha as well as proteins regulated by HIF complexes, such as carbonic anhydrase 9 (CA9) and vascular endothelial growth factor (VEGF)." (PMID 28430808, 2017). "The utility of CA9 as a hypoxia marker was confirmed using another intrinsic hypoxia marker GLUT1 and the extrinsic hypoxia marker EF5 in sequential Calu-6 tumor sections." (PMID 27020103, 2016). "Tumor hypoxia, vascular endothelial growth factor (VEGF), proliferation, and microvascular density (MVD) were assessed by immunostaining for HIF-1α and carbonic anhydrase-9 (CA-9), VEGF, Ki67, and cluster of differentiation-31, respectively." (PMID 26937938, 2016). "We first evaluated the simultaneous expression of EpCAM, CA9 and CD147 in serial sections of tumor specimens collected from the RCC patient cohort spanning 4 different clinical stages by IHC analysis." (PMID 27494883, 2016). "In this study, we identified that CA9 levels in serum are correlated with tumor tissue CA9 levels in clinical CRC patients and CA9 can as a biomarker for hypoxic tumor diagnosis." (PMID 26447758, 2015). "The current study aimed to determine the expression of hypoxic markers, including HIF-1α, CA9, GLUT1, and VEGF, in STS using immunohistochemistry, and to analyze the impact of overexpression on the clinicopathological features of tumor aggressiveness." (PMID 25789026, 2015). "Almost all newly developed hypoxic tumor areas labeled by EF5 (red) showed the apparent expression of hypoxia response protein CA9 (red)." (PMID 26416246, 2015). "Among the members of the CA isozyme family, CA2, CA9, and CA12 have been shown to be related to tumor genesis." (PMID 24959000, 2014). "IHC staining fractions for CA9, EGFR, MCT4, pAKT, GLUT1 and PIMO, as well as the BrdU LI, VD and PF of the microscopy-imaged tumor sections were analyzed." (PMID 24571588, 2014). "Therefore, CA9 overexpression may be an indicator of early stages of tumor development." (PMID 23671581, 2013). "For CA-9 and EF5 (hypoxia) in the epithelial components of the tumor there was a significant (p < 0.001) increase with passage number." (PMID 24213469, 2012). "Extracellular acidosis, a common feature in tumours, increases HIF-1α protein accumulation and CA9 transcriptional activity under normoxic conditions." (PMID 21910893, 2011). "Among tested genes, our study identified CA9, GLUT1 and possibly LOX as highly specific biomarkers of tumor hypoxia in vivo." (PMID 21306648, 2011). "A strong positive correlation between regional CA9, LOX and GLUT1 mRNA transcript levels and FAZA retention was revealed in a human tumor model suggesting that these genes display high hypoxia-specificity in vivo and are superior to LDH and GAPDH." (PMID 21306648, 2011). "The relationship between relative CA9, GLUT1 and LDH expression and FAZA retention in SCCVII tumors was very similar to the human tumor xenograft." (PMID 21306648, 2011). "Carbonic Anhydrase 9 (CAIX, G250/MN) is a membrane-spanning protein involved in the enzymic regulation of tumor acid-base balance." (PMID 20523727, 2010). "The staining of pimonidazole, HIF-1α, and CA9 was heterogeneously positive in both the OCUM-12 and the OCUM-12/Hypo tumours." (PMID 20145613, 2010). "In vivo experiments showed that CA9 gene silencing alone led to a 40% reduction in xenograft tumour volume, and the silencing of both CA9 and CA12 resulted in an 85% reduction in tumour volume." (PMID 20398423, 2010). "Carbonic anhydrase 9 was detected in 11 of 12 (92%) GBM tumours (percentage of positive cells: 1–80%) and in 8 of 11 (73%) grade 3 tumours (range of positive cells: 1–40%)." (PMID 19920819, 2009).
tumor (continued). "Vascular endothelial growth factor (VEGF), VEGFR-2, carbonic anhydrase 9 (CA9) and hypoxia-inducible factor-2α (HIF-2α) were assessed semiquantitatively in archival tumours using immunohistochemistry and were correlated with outcome." (PMID 19920819, 2009). "CA9 accelerates CO2 removal from the intracellular milieu as well as facilitates HCO3 - recycling; thus, it serves to protect the tumor cells from acidosis." (PMID 19619339, 2009). "Carbonic anhydrase 9 (CA9), such as hypoxia-inducible factor 1α (HIF-1α), is known to be a marker of hypoxia, but its role in a hypoxic tumour microenvironment is still unclear." (PMID 18841153, 2008). "We investigated the expression of CA9 in ESCC at both the protein and mRNA levels, and found that CA9 protein was expressed in tissue samples from 76 of 127 (59.8%) tumours." (PMID 18841153, 2008). "CA9, similar to HIF-1, is a member of the hypoxia-induced pathway and is thought to be expressed specifically around the tumour centre, where hypoxic conditions prevail." (PMID 18841153, 2008). "In univariate Cox proportional hazards analysis, primary tumour (T), regional lymph node metastasis (N), distant metastasis (M), TNM stage (S) and CA9 expression were the strongest prognostic factors for cancer-specific survival." (PMID 18841153, 2008). "It has also been revealed that EGFR and HER-2 can potentiate tumour cell adhesion to endothelial cells, by enhancing the synthesis of hypoxia-inducible factor (HIF)-1α, and/or carbonic anhydrase-9 through a PI3 kinase-dependent pathway." (PMID 14710236, 2004). "The median carbonic anhydrase 9 (CA9) expression (M75 antibody), as a marker of hypoxia, (intensity × % of stained tumour cells) was 0 in the BC metastases and 53 in the CRC metastases (P<0.0001)." (PMID 15054467, 2004). "Using the marker carbonic anhydrase 9 (CA9), we found evidence of hypoxia in only 17% of the cutaneous deposits with an infiltrative growth compared with 71% of the tumours with an expansive, nodule-forming growth (P=0.02)." (PMID 15054467, 2004). "Taken together, our findings suggest that the dysadherin/CA9 axis facilitates CRC cell adaptation to an acidic TME by promoting metabolic reprogramming, activating CAFs, and enabling immune evasion, thereby contributing to enhanced tumor malignancy." (PMID 41535258, 2026). "In contrast, while similar studies performed on the liver metastasis also showed that the tumor cells expressed PAX8, the percentage of cells expressing other renal markers was markedly higher than in the brain lesion with CA9 expression measured at 77.0% and CD10 expression at 29.5%." (PMID 39833894, 2025). "CA9 is constitutively overexpressed in ccRCC due to VHL gene loss, with 88.2% of tumours showing CA9 upregulation independent of VHL mutation status." (PMID 41375084, 2025). "Among them, tumor cells showed moderate positivity for CK7; CA9 showed diffuse strong positive membrane staining, completely outlining the cell membrane; ELOC was moderate positive, mainly localized in the nucleus, with varying degrees in staining intensity and range." (PMID 41306531, 2025). "At the same time CA9 was strongly upregulated in SW982 cells even after reoxygenation, suggesting long-lasting transcriptional effects of acid based regulation in maintaining cell viability in metabolically challenging tumor microenvironments." (PMID 41174561, 2025). "Most notably, in vivo experimental data are currently lacking to confirm whether ICT can similarly modulate the expression of CA9, UCK2, FABP5, and CYP2C9, as well as remodel the tumor immune microenvironment in living organisms." (PMID 41357200, 2025).
tumor (continued). "Under hypoxic conditions, the accumulation of hypoxia‐inducible factor 1α (HIF‐1α) promotes the expression of carbonic anhydrase 9 (CA9), a member of the carbonic anhydrase family, which selectively expresses on the surface of tumor cells and gastrointestinal epithelial cells." (PMID 40873634, 2025). "Based on the result that HBO downregulates pH‐regulatory genes, including CA9, we hypothesized that HBO treatment could lower the intracellular pH of tumor cells to augment pH‐responsive tumor therapies." (PMID 40873634, 2025). "Moreover, mechanism studies revealed that ZNF674-AS1 interacted with IGF2BP3 to regulate the transcriptional level of Carbonic Anhydrase IX (CA9), a key enzyme involved in tumor growth and correlated with the clinical prognosis of NB patients." (PMID 38177154, 2024). "Moreover, hypoxia induces the transcription of genes that are crucial for tumor survival and progression, including vascular endothelial growth factor (VEGF), carbonic anhydrase-9 (CA IX), and glucose transport proteins (GLUT-1 and GLUT-3)." (PMID 39459028, 2024). "Despite the critical involvement of CAs, particularly membrane associated CA isoform CA9, in regulating pH, hypoxia, metabolism and tumor development, no reports described potential role of CA9 or per se any CA isoforms in EBV mediated B-cell lymphomagenesis." (PMID 38530845, 2024). "On the other hand, in adenocarcinoma, CA9 accurately reflected tumor hypoxia, which may explain the increased sensitivity of [18F]FDG PET/CT in the CA9-positive group of adenocarcinoma." (PMID 39471162, 2024). "So, in CA9-positive group of SCC, CA9 failed to reflect tumor hypoxia because of frequent hypoxic lesions caused by inflammation." (PMID 39471162, 2024). "For example, unlike any other CAs, CA9 through its proteoglycan domain contributes to cell adhesion property, thus plays an important role in tumor invasiveness." (PMID 38530845, 2024). "To explore TAGLN and HDAC2 expression in GBM patient surgical specimens, we performed IHC staining and observed that HDAC2 (which is a hypoxia‐related gene), TAGLN, CA9 (a hypoxic marker), and HIF1α were all located in GBM tumor cell nuclei and highly expressed in pseudopalisades (upper)." (PMID 38087889, 2024). "In addition to VEGF, VEGF receptor-2 (VEGFR)-2, and CA9, which are regulated by hypoxia-inducible factor 1 subunit alpha (HIF-1a), exosomes have emerged as a novel source of non-invasive tumor biomarkers." (PMID 37762660, 2023). "All tumour cells were negative for vimentin, CA9, CD10, P504s, CK20, TFE3, TFEB, HMB45, ALK and FOXI1." (PMID 36816543, 2023). "Combinatorial genetic depletion of CA9 and NFS1 expression, or pharmacologic inhibition of CAIX/XII in combination with NFS1 depletion, results in increased cellular iron pools, increased lipid peroxidation and increased ferroptosis of tumour cells." (PMID 38099193, 2023). "Furthermore, the most relevant carbonic anhydrases for GB, CA9 and CA12, were described as tumor cell-intrinsic carbonic anhydrases in GB and other tumor entities." (PMID 38139457, 2023). "Because CA9 has a higher oxygen threshold than PIMO, it is not unexpected that we observed CA9 staining closer to tumor blood vessels." (PMID 37285434, 2023). "The downregulation of HIF-1α and carbonic anhydrase 9 (CA-IX) and increased vascular permeability after IRE suggest that IRE may also increase the number and action of local T cells, NK cells by alleviating tumor hypoxia." (PMID 36081554, 2022). "ccRCC 2D cultures (from Grade 2 and 3 tumours) were also established in serum-supplemented DMEM, with over 90% of cells expressing cytokeratin, vimentin and CD13, and over 60% of cells positive for carbonic anhydrase IX (CA9), a marker specific for ccRCC." (PMID 35102500, 2022). "CA9 is a hypoxia-inducible, membrane-bound extracellular CA catalyzing the reversible hydration of CO2 at the cell surface and is thought to promote tumor growth by protecting tumor cells from acidosis." (PMID 36380966, 2022).
tumor (continued). "We used fresh LGG tumor specimens for IF detection and found that TNC and CA9 were co-expressed." (PMID 35371015, 2022). "CA9 IHC staining previously performed on the samples and used as a marker of hy-poxia shows positive versus negative tumours had fewer CD8+ cells (p = 0.03, n = 111)." (PMID 36612036, 2022). "In tumours with above median ascorbate content, HIF-pathway activity as a whole was significantly suppressed (p = 0.005), and several members of the pathway showed decreased expression (carbonic anhydrase-9 and glucose transporter-1, both p < 0.01)." (PMID 35419292, 2022). "This combined perturbation of CA9 and VEGF triggered by specific ENCTAC degradation may provide the possibility to enhance sensitivity toward tumor therapies." (PMID 36516252, 2022). "Finally, GLUT3 out-performs other established hypoxia markers; GLUT3 staining in PDX specimens detects 2.6–8.3 times more tumor area compared to a mixture of GLUT1 and CA9 antibodies." (PMID 35328229, 2022). "We found a higher percentage of CA9+ cells with increasing tumour grade, no CA9+ cells were found in matched healthy tissue." (PMID 35102500, 2022). "They noticed negative conversion of CA9 and durable responses to such therapy, highlighting the importance of vascular normality in tumor targeted therapies." (PMID 35145911, 2021). "First, we categorized clustered data into tumor and stromal populations using a panel of markers for each (epithelial: AQP1, AQP2, EPCAM; endothelial: PLVAP, CD31, CD34; fibroblast: PDGFRα, PDGFRβ; immune: CD45; tumor cell: CXCR4, VIM, KRT18, PAX8, PAX2, CA9, CD10)." (PMID 34884982, 2021). "HIF-1 is able to promote the growth of endothelial cells after radiotherapy by inducing the expression of key downstream genes, including vascular endothelial cell growth factor (VEGF), carbonic anhydrase (CA9), and glucose transporter (GLUT1), thus promoting the overall tumor radioresistance." (PMID 33869184, 2021). "In our study, the in vivo findings on tumor oxygenation and blood volume were validated by rigorous analysis of histologic gold standards of vascularity (CD31) and tissue hypoxia (pimonidazole, CA9)." (PMID 34335966, 2021). "Strikingly, this strong CA9 increase was significantly correlated with tumor down-staging and node sterilization, but not with the degree of surviving tumor cells relative to fibrosis (i.e., tumor regression grade) of the surgical specimen." (PMID 32781554, 2020). "Once the nodules reached the established tumor mass threshold (2.2 cm3) the individuals were sacrificed, and the nodules analyzed by immunohistochemistry staining with mouse anti-MCM2 and mouse anti-CA9 antibodies." (PMID 33153038, 2020). "The histological observations raised the speculation that a response from CA9-expressing TME stromal cells to the induction NACT, in addition to the response from the actual tumor cells, might have been conditional for the favorable survival outcome." (PMID 32781554, 2020). "Therefore, we selected carbonic anhydrase 9 (CA9), CD70, and CD147 as highly promising tumor specific markers on exosomes in RCC, since they have been shown to be upregulated during tumor development and progression in clear cell RCC." (PMID 33276608, 2020). "In contrast to EpCAM, CA9, CD70, and CD147 could represent promising markers to identify tumor-specific EVs in ccRCC." (PMID 33276608, 2020). "High CA9 expression had a mean FIL score of 0.25 vs. 0.06 in tumours lacking CA9 expression (p = 0.008)." (PMID 32066909, 2020). "Immunohistochemically, the tumor was positive for carbonic anhydrase 9 (CA9) but negative for cytokeratin 7 (CK7), suggestive of metastatic RCC." (PMID 32347406, 2020). "As HIF-1α induces the expression of genes related with tumor survival, we assessed the mRNA levels of CCND2, VEGF, BNIP3L, and CA9, and found that CCND2, VEGF, BNIP3L, and CA9 were upregulated when spheroids were treated with OA, whereas their mRNA levels decreased upon FABP5 or HIF-1α silencing." (PMID 33128030, 2020).